KIT (KIT proto-oncogene, receptor tyrosine kinase)
Diseases named in the same sentence as KIT in open-access papers (continued):
Sharing a sentence is not in itself a finding about the gene and the disease.
melanoma (continued). "In light of these data, we explored the response of KIT mutated melanoma cell lines to KIT inhibitors under specific cellular conditions and microenvironments." (PMID 32344828, 2020). "In a phase-II clinical trial conducted in 28 patients with melanoma harboring c-KIT mutations or amplifications, treatment with imatinib yielded a durable response rate of 16%, with responses lasting more than one year." (PMID 32517051, 2020). "To better understand the mechanism by which KIT mutated melanoma resist to KIT inhibitors, we used three melanoma cell lines with different KIT alterations: M230 (L576PKIT), HBL (D820YKIT), and LND1 (amplification of WTKIT)." (PMID 32344828, 2020). "As these data suggested the importance of the MAPK pathway in resistance to nilotinib, we analyzed its activation in situ in KIT-mutated melanoma." (PMID 32344828, 2020). "Melanoma cells expressing dual activating mutations in KIT (e.g., L576P/T670I or A829P) while being resistant to imatinib, nilotinib, and dasatinib, did exhibit increased sensitivity to dual inhibition of the MAPK and PI3K pathways." (PMID 32517051, 2020). "In the double wild type mucosal melanoma cohort the KIT mutation frequency was found to be comparable (41.2%)." (PMID 31848942, 2020). "KIT gain-of-function mutations have been shown to drive the formation of rare acral and mucosal melanoma subtypes." (PMID 32455885, 2020). "The purpose of this study was to asses the molecular epidemiology of KIT mutation in melanoma in a Central European country (Hungary), since data are almost absent with an exception of a Slovenian report on a small cohort." (PMID 31848942, 2020). "Superior response rates in patients harboring KIT mutations in exon 11 or 13 were noted, likely representing driver mutations responsible for melanoma growth." (PMID 33233603, 2020). "Although genetic mutations like BRAFV600, NRAS and KIT are crucial in melanoma initiation, progression and metastasis, the pursuit of these targets often disappointed to some proportion of melanoma patients." (PMID 33136551, 2020). "We showed that although KIT inhibition markedly decreased cell viability in melanoma cell lines with distinct KIT mutations, this effect was lessened in the presence of FGF2 due to inhibition of BIM expression by MAPK pathway activation." (PMID 32344828, 2020). "Because of the relative rarity of c-KIT mutations, the understanding of targeted therapy to treat melanoma is scarce." (PMID 32429485, 2020). "In BRAF/NRAS, wild-type melanomas and the mutations or amplifications of the c-KIT gene must be analyzed." (PMID 32054005, 2020). "Conversely, nilotinib also suppresses the STAT3 pathways that can lead to a reduction in BCL2 expression that acts in concert with BIM induction to trigger an apoptotic response and cell death in KIT-mutated melanoma." (PMID 32344828, 2020). "Nine of these patients had driver mutation data derived from the tumor specimen: 5/9 patients had BRAF/NRAS/KIT wild type melanoma, whereas 4/9 patients had BRAF or NRAS driver mutations identified in the tumor." (PMID 32785074, 2020). "In contrast, clinical studies examining the efficacy of KIT inhibitors in patients with KIT-mutated melanoma have been underwhelming compared with GIST." (PMID 32344828, 2020). "More recently, ponatinib has been shown to exhibit greater potency than imatinib in inhibiting tumor growth in melanomas harboring KIT mutations, likely because of an increased ponatinib-KIT affinity." (PMID 32517051, 2020). "BRAF, NRAS, and KIT are three well-known genes associated with melanoma, and BRCA1 and BRCA2 are two representative genes associated with breast cancer." (PMID 33121438, 2020). "It is another question what the mutation pattern of KIT in melanoma is as compared to the KIT-mutant prototype cancer, GIST." (PMID 31848942, 2020). "In the context of melanoma where the L576P is the most common KIT mutation, patients show increased sensitivity to dasatinib." (PMID 32517051, 2020).
melanoma (continued). "A melanoma patient treated with imatinib developed both a L576P KIT mutation and a CTNNB1 S33C mutation." (PMID 32283832, 2020). "The presence of mutations of NRAS, and KIT genes has also been correlated to the subtype and localization of melanoma." (PMID 31274706, 2020). "Activating somatic mutations in the KIT proto-oncogene are found in approximately 2–8% of melanomas, especially in those arising in mucosal and acral localizations (10–20% of the cases, respectively)." (PMID 33036192, 2020). "Since KIT mutations predominate over BRAF or NRAS mutations in mucosal melanomas, this result suggests a special cooperativity between KIT gain of function and SPRED1 loss." (PMID 32455885, 2020). "Our study aims to evaluate and review other studies that present the frequency of mutations of BRAF, NRAS, and KIT genes for different populations, and analyse correlation to their clinical-pathological characteristics and to the demographics of melanoma." (PMID 31274706, 2020). "KIT mutations occur in 35–40% of mucosal and acral melanoma, and 28% of melanomas on chronically sun-damaged skin." (PMID 33109256, 2020). "Several studies have reported durable tumor responses to KIT inhibition by imatinib, nilotimib, sorafenib, dasatinib, and sunitinib in patients with melanoma harboring KIT mutations." (PMID 32850452, 2020). "Tyrosine kinase inhibitors (imatinib, nilotinib and dasatinib) have also shown benefits for melanoma patients with activating KIT mutations." (PMID 31277584, 2019). "Minor percentages of melanomas have activating mutations in the KIT gene, most common in mucosal melanomas derived from the genital regions or mutations in G Protein Subunit Alpha 11 (GNA11) or G Protein Subunit Alpha q (GNAQ) genes in uveal melanomas." (PMID 30884760, 2019). "Other research studies have reported falling levels of circulating free DNA (ctDNA) for tumor survival-promoting mutant kinase BRAF, NRAS, and KIT alleles in melanoma patients who are undergoing immunotherapy." (PMID 30941125, 2019). "Our study supports these previous reports, and detected KIT mutations in 11% of mucosal melanomas, particularly in the vulval and vaginal sites." (PMID 30847022, 2019). "Diverse KIT mutations were found in various human cancers, including melanoma, and one variant showed a significant association with cutaneous invasion, melanoma development, and tumor ulceration in the MeLiM strain." (PMID 31717496, 2019). "We found that SF3B1 and KIT mutations predominantly occurred in melanomas originating in vulval/vaginal sites." (PMID 30847022, 2019). "Targeted therapy against v-kit Hardy-Zuckerman 4 feline sarcoma viral oncogene homolog (KIT) activating mutations, seen in around 10–22% of mucosal melanomas, has been tested in clinical trials but results have been underwhelming." (PMID 31398831, 2019). "Despite the clinical benefit achieved with KIT inhibition in select patients with melanoma harboring KIT mutations, most patients ultimately experience disease progression." (PMID 31398831, 2019). "A fraction of mucosal melanomas presents with KIT mutations that are targetable with KIT inhibitors." (PMID 31336679, 2019). "The second patient who received targeted therapy followed by immunotherapy had KIT mutation in melanoma and received imatinib followed by combination imatinib + pembrolizumab." (PMID 31384390, 2019). "KIT is the most frequently mutated gene in melanomas arisen in mucosae worldwide (10%–30%), with an unequal geographical distribution of the mutation prevalence according to the population of the origin of the patients." (PMID 31581559, 2019). "A total of 17 unique KIT mutations were detected in 22 melanomas, include one with two KIT mutations and one with 3 KIT mutations." (PMID 31277584, 2019). "Both the melanomas harbor KIT mutation in approximately 15% of the cases; BRAF or NRAS mutation is found in approximately 10–15% of acral melanoma, but these mutations are less frequent in mucosal melanoma." (PMID 30675668, 2019).
melanoma (continued). "Recent studies have reported that sunitinib controls c-KIT or non c-KIT mutated malignant melanoma (MM)." (PMID 29416656, 2018). "This suggests that KIT mutations have a role in the physiopathogeny and, therefore, are a potential therapeutic target in these subtypes of melanoma." (PMID 29796159, 2018). "KIT is another important checkpoint for the targeted therapy in melanomas, since molecules as imatinib, nilotinib and apatinib can affect melanoma cells with KIT mutations." (PMID 30181807, 2018). "The objective of the present study was to evaluate the frequency of KIT mutations and their prognostic value in a significant number of head and neck mucosal melanomas." (PMID 29796159, 2018). "Depending on the presence of NRAS- or c-KIT-mutations, either MEKi, c-KIT inhibitors, immunotherapy with anti-PD-1 checkpoint blockers, or polychemotherapy are recommended for the treatment of advanced non-BRAFV600mut melanoma." (PMID 29794999, 2018). "Generally, our findings support existing literature stating that KIT mutations are more frequent in melanomas of the genital area followed by melanomas of the head and neck and the anorectal area." (PMID 28380455, 2017). "Of the 19 non‐sun‐induced melanomas in the cohort (uveal, n = 2; acral/mucosal, n = 17), only four cases contained recurrent mutations in KIT or GNA11." (PMID 28267273, 2017). "In GIST tumors, activating mutations of c-KIT were detected, but also the loss or down-regulation of the c-KIT can be observed linked to neoplastic transformation as for example in breast carcinoma and melanoma." (PMID 28301608, 2017). "Imatinib-a receptor tyrosine kinase inhibitor-showed high response rates and beneficial effects in patients harboring a melanoma with mutations in the exons 11 and 13 of the KIT gene." (PMID 28350340, 2017). "Inactivating mutations of KIT lead to piebaldism, whereas activating mutations in KIT lead to melanoma and mutations in the KIT ligand (KITLG) cause the Steel phenotype in mice and progressive familial hyperpigmentation in humans." (PMID 28170433, 2017). "In a multicenter phase II study with Nilotinib, a novel phenylaminopyrimidine derivate with potent activity against KIT, KIT amplification alone was detected in 35.7% of melanoma and combined with KIT mutations in 4.8%." (PMID 29312620, 2017). "RAC1 mutations are present in all melanoma subtypes, which can be explained by its position at the crossroads of KIT/NRAS/BRAF/MAPK signaling and the PI3K/PTEN/AKT axis." (PMID 28265786, 2017). "The prevalence of gene mutations varied by melanoma location, as most of the KIT mutated melanomas were distributed in chronically sun-damaged skin and acral melanomas, and were significantly associated with ALM [p = 0.004; OR = 4.4 (1.6–12.1)]." (PMID 28356599, 2017). "Limited benefit was seen with imatinib therapy in an unselected population, but there has been interest in the use of c-KIT targeting therapies in KIT-mutated melanoma." (PMID 28428884, 2017). "Two responses were seen among 35 patients in a patient with wild-type GIST and in one with KIT-mutated melanoma." (PMID 28428884, 2017). "Several trials have reported varying degrees of benefit for the role of tyrosine kinase inhibitors including imatinib, nilotinib, and dasatinib in KIT-mutated melanomas." (PMID 28428884, 2017). "Other activating oncogenic events, e.g. gene amplifications or gain-of-function mutations of KIT are more frequently detected in mucosal melanomas." (PMID 28380455, 2017). "With lower frequencies, KIT mutations have been observed in mucosal and acral melanomas and melanomas with sun-damaged skin." (PMID 28567163, 2017). "Genetic alterations of KIT, including mutations and copy number increases, have been reported to occur in up to 39% of mucosal melanomas." (PMID 28380455, 2017). "Up to 40% of mucosal melanoma cells either overexpress the cKit protein or express gain-of-function mutations in KIT protooncogenes, or both." (PMID 28638859, 2017).
melanoma (continued). "Wild-type c-KIT expressing GIST and KIT-mutated melanoma represent minority subgroups of their respective diseases with limited treatment options, highlighting the need for new therapeutic developments." (PMID 28428884, 2017). "The KIT proto-oncogene receptor tyrosine kinase gene is frequently mutated in acral and mucosal melanoma as well as in melanomas of chronically sun-damaged skin." (PMID 28350340, 2017). "Mutations in the receptor tyrosine kinase c-KIT (KIT) are frequent oncogenic alterations in melanoma and are predominantly detected in tumors of acral, mucosal, and chronically sun-damaged skin." (PMID 27322141, 2016). "We report a case of KIT-mutant vaginal mucosal melanoma with a mixed response to imatinib that caused the drug to be withdrawn after only 8 weeks." (PMID 27502704, 2016). "It is difficult to conclude that germline KIT mutation can induce melanoma based on the only observation." (PMID 27777718, 2016). "The most frequently investigated KIT mutations in melanoma concern the exons 11 and 13 that resulted partially responsive to KIT inhibitors." (PMID 26863566, 2016). "This described phenomenon is also found with MEK inhibitors in MAPK-driven melanoma with KIT or NRAS mutations." (PMID 27250023, 2016). "Respectively 50%, 30%, 33% and 20% of BRAF-, NRAS-, c-KIT-mutated or wild type melanomas were successfully engrafted." (PMID 26909610, 2016). "These melanoma types frequently have activating genetic alterations in the KIT signaling pathway, represented predominantly by mutations and amplifications of KIT itself." (PMID 27322141, 2016). "In fact, melanoma patients with a KIT mutation affecting a recurrent hot spot, such as the L576P or K642E mutation, have better clinical outcomes than those without a hotspot mutation." (PMID 26863566, 2016). "Although BRAF mutation is the dominant mutation in melanoma, mutations in KIT gene have also been reported." (PMID 27777718, 2016). "Using human skin reconstructs grafted onto immunodeficient mice, we studied the migration and growth of genetically engineered melanocytes and melanoma cells expressing relevant KIT mutations." (PMID 27322141, 2016). "A review of literature reports that 14 % of mucosal melanomas harbor activating c-KIT mutations; 5 % showed BRAF mutation and 14 % oncogenic mutations in NRAS, which is much lower than the reported BRAF prevalence (56–59 %) in cutaneous melanoma." (PMID 26420268, 2015). "Imatinib is a small molecule inhibitor of KIT that inhibits proliferation and induces apoptosis in melanoma cells harbouring KIT mutations, associated with significant clinical response in these patients." (PMID 26334521, 2015). "Recently, the occurrence of KIT epigenetic silencing in cutaneous melanomas has been demonstrated, supporting earlier studies that had shown decrease of KIT expression associated with melanoma progression." (PMID 26106605, 2015). "In contrast to BRAF mutated melanoma, the kinase inhibitor imatinib has proven efficacy in patients with advanced melanoma harbouring KIT mutations." (PMID 26420268, 2015). "KIT mutations are found at low frequencies (≤10 %) in melanomas arising from mucosal or acral lentiginous surfaces." (PMID 26420268, 2015). "An interesting option for c-KIT mutated melanoma and GIST patients is a dose escalation schedule with cycles of imatinib followed by ipilimumab, currently underway (NCT01738139)." (PMID 25709607, 2015). "Increased levels of the receptor tyrosine kinase CD117 (c-KIT) on enriched melanoma cells (CD45−) were associated with distant metastasis and poor survival outcomes but this was not statistically significant (p = 0.07)." (PMID 24435119, 2014). "Recently, KIT-activating mutations were reported in 21% of mucosal melanomas, 11% of acral melanomas, and 16.7% of melanomas arising in chronically sun-damaged skin." (PMID 24963404, 2014).
melanoma (continued). "PI3K/Akt pathway activation in melanoma can also occur through mutational activation of PI3KCA along with the mutational activation of upstream receptor tyrosine kinases such as c-KIT and EGFR." (PMID 25168062, 2014). "In our study, the median TTP for patients with melanoma and a KIT genetic aberration (mutation or amplification) was 4.7 months (95% CI: 1.3 to 7.4 months) and was independent of melanoma type (log-rank p = 0.98) or KIT aberration sub-type (log-rank p = 0.20)." (PMID 25609545, 2014). "Higher frequency of KIT mutation in melanoma is associated with older patients and the acral and mucosal melanoma subtypes." (PMID 24591764, 2014). "Approximately 70% of KIT mutations identified in melanoma are found in exon 11, most commonly L576P, and in the kinase domain in exon 13, most often K642E." (PMID 24743024, 2014). "The mutational status of BRAF, RAS, GNAQ, GNA11 and KIT genes in Grey horse melanomas was determined by direct sequencing." (PMID 25413220, 2014). "The CD45− enriched melanoma cells displayed differential binding to CD117 (c-KIT), with higher levels associated with decreased DMFS on univariate analysis with borderline significance (HR = 1.56; p = 0.07)." (PMID 24435119, 2014). "Recent studies also illustrated the effectiveness of Imatinib in patients with advanced melanoma harboring mutations or amplification of the KIT protooncogene." (PMID 24963404, 2014). "With regard to the effects of DNA hypermethylation on melanoma patients' survival, correcting for clinical cofounders, only the KIT gene was associated with a lower overall survival rate." (PMID 24832207, 2014). "The majority of mutations of KIT found in melanoma also occur in other cancers that are responsive to KIT inhibitors." (PMID 24743024, 2014). "KIT is a receptor tyrosine kinase activated by binding of the cytokine stem cell factor (SCF); mutations and amplification of KIT are found in particular subsets of melanoma." (PMID 24743024, 2014). "Nevertheless, case reports continued to surface that demonstrated the efficacy of imatinib in melanoma patients with specific KIT genetic aberrations, such as mutation K642E and a small duplication." (PMID 24743024, 2014). "PDGFRA and KIT (CD117) are transmembrane receptor tyrosine kinases associated with certain cancers including melanoma and acute myeloid leukemia, and activating mutations in both genes have been associated with tumorigenesis." (PMID 25329450, 2014). "Metabolic response by 18F-FDG-PET/CT is associated with exon 11 KIT mutational status in patients with mucosal melanoma, acral melanoma or melanoma arising on chronically sun damaged skin treated with imatinib." (PMID 25609545, 2014). "KIT mutations are rare in melanoma, but the availability of selective inhibitors for KIT has prompted interest in targeting this oncogene." (PMID 24743024, 2014). "The c-KIT up-regulation is often associated with increased cell proliferation; its down-regulation in D6 treated melanoma cells was confirmed by western blot analysis." (PMID 23642048, 2013). "Another possible targeted treatment for patients with metastatic melanoma is available for melanoma cells with a KIT mutation." (PMID 23420786, 2013). "KIT is activated by mutation in only 2–6% of cutaneous melanomas but aberrations in KIT (mutation, amplification) have been reported in melanomas of acral (36%), mucosal (39%), and chronic sun-damaged/lentiginous (28%) types." (PMID 24416617, 2013). "Of the melanoma patients treated with Sunitinib, 11% had mutations in KIT [other patients presented with mutations in BRAF (23%), NRAS (14%), or GNAQ (0%)]." (PMID 23515890, 2013).